STK4 (serine/threonine kinase 4)
Diseases named in the same sentence as STK4 in open-access papers (continued):
Sharing a sentence is not in itself a finding about the gene and the disease.
cervical cancer (5 papers, 2020 to 2023). A primary or metastatic malignant neoplasm involving the cervix. "We showed that loss of either oncoprotein from cervical cancer cells resulted in the re-appearance of STK4; however, ectopic expression of the oncoproteins in HPV- cells was not able to fully recapitulate the loss of STK4 observed in cervical cancer cells." (PMID 32555725, 2020). "In this study, we used a combination of patient samples and cancer cell lines to provide the first evidence that the loss of the STK4 is associated with the YAP-mediated proliferation of cervical cancer cells." (PMID 32555725, 2020). "STK4 is significantly decreased in HPV-associated cervical cancer via HPV E6 and E7 oncoproteins suppressing STK4 mRNA and increasing YAP-dependent gene expression, which aids HPV replication and tumor progression." (PMID 36960048, 2023). "Critically, knockdown of STK4 partially restored cervical cancer cell proliferation, suggesting that the observed effects of miR-18a inhibition are in part dependant on the inhibition of STK4 gene expression." (PMID 32555725, 2020). "The HPV E6 and E7 oncoproteins maintained low STK4 expression in cervical cancer cells by upregulating the oncomiR miR-18a, which directly targeted the STK4 mRNA 3’UTR." (PMID 32555725, 2020). "This would indicate that in these cells STK4 is the predominant target, although it would be useful to identify the additional mIR-18a targets that regulate cervical cancer cell proliferation." (PMID 32555725, 2020). "Cells transfected with the miR-18a antagomir showed increased luciferase levels, suggesting that miR-18a directly regulates STK4 gene expression in HPV+ cervical cancer cells." (PMID 32555725, 2020). "Our results identify STK4 as a key cervical cancer tumour suppressor, which is targeted via miR-18a in HPV positive tumours." (PMID 32555725, 2020). "Levels of STK4 were selectively reduced in HPV+ cervical cancer lines and these findings were supported by clinical data, showing that STK4 expression negatively correlates with cervical disease progression and is markedly down regulated in cervical cancer." (PMID 32555725, 2020). "Together, these data demonstrate that miR-18a activity promotes proliferation in HPV+ cervical cancer by suppressing STK4 gene expression to inactivate the Hippo pathway." (PMID 32555725, 2020). "Building on this, we were able to show that decreased STK4 mRNA expression is a common occurance in cervical cancers." (PMID 32555725, 2020). "Importantly, STK4 overexpression in HPV+ cervical cancer cells led to an inhibition of YAP function, as seen by the increased YAP phosphorylation and a corresponding decrease in cell proliferation." (PMID 32555725, 2020). "Thus, overexpression of STK4/STK3 in HPV+ cervical cancer cells reconstitutes a functionally active Hippo signalling pathway capable of excluding YAP from the nucleus and reducing YAP-regulated gene expression." (PMID 32555725, 2020). "This suggests that the tumour suppressor activity of STK4/STK3 may be specific to HPV+ cervical cancer cells and warrants further investigation." (PMID 32555725, 2020). "Together, these data show that Hippo re-activation results in a defect in cell proliferation and the ability of HeLa and CaSKi cells to form colonies in an anchorage dependent or independent manner, highlighting a potential tumour suppressor role for STK4/STK3 in HPV+ cervical cancer cells." (PMID 32555725, 2020). "Interestingly, miR-18a knockdown increased STK4 expression and activated the Hippo pathway, significantly reducing cervical cancer cell proliferation." (PMID 32555725, 2020). "To understand how STK4 protein levels were reduced in HPV+ cervical cancer cells, we first measured whether inhibition of protein degradation restored its expression, as HPV E6 has previously been shown to stabilise YAP, a downstream target of STK4." (PMID 32555725, 2020).
cervical cancer (continued). "Importantly, STK4 levels were also lower in cytology samples from patients with cervical disease and in cervical cancer samples compared to healthy controls." (PMID 32555725, 2020). "In contrast, overexpression of STK4 had minimal impact on the growth of HPV- cervical cancer cells." (PMID 32555725, 2020). "Thus, it was pertinent to investigate the consequences of re-activating Hippo signalling in cervical cancer cells by the re-introduction of STK4 or STK3." (PMID 32555725, 2020). "In addition to lncRNAs, HPV also alters the expression of other ncRNAs such as miRNAs, and miR-18a, which directly targets mRNA of the Hippo pathway regulatory kinase STK4, has been found overexpressed in cervical cancer cell lines in which STK4 is downregulated." (PMID 35632705, 2022). "Thus, we conclude that in cervical cancer cells the HPV oncoproteins are necessary but not sufficient for the loss of STK4." (PMID 32555725, 2020). "In patient samples, a significant down-regulation of STK4 was only observed in CIN2 and CIN3, as well as in cervical cancer." (PMID 32555725, 2020). "We found significant down-regulation of the master Hippo regulatory kinase STK4 (also termed MST1) in cervical disease samples and cervical cancer cell lines compared with healthy controls." (PMID 32555725, 2020). "Mechanistically, we discovered that in HPV+ cervical cancer cells HPV E6 and E7 expression led to suppression of STK4 mRNA levels and this was achieved through an increase in the mature form of miR-18a, which directly targeted the 3’UTR of the STK4 mRNA." (PMID 32555725, 2020). "Additionally, our studies have demonstrated that expression of the serine/threonine-protein kinase 4 (STK4), a key upstream negative regulator of YAP1/TAZ activity, is significantly downregulated in HPV+ cervical cancer." (PMID 33427604, 2021). "We hypothesized that these oncoproteins were responsible for the reduction in STK4 mRNA levels and subsequent protein expression observed in HPV+ cervical cancer." (PMID 32555725, 2020). "In primary keratinocytes activation of YAP appears to be independent of a reduction in STK4 expression, whilst re-expression of this protein in cervical cancer cells is deleterious to cell proliferation." (PMID 32555725, 2020). "Whilst suppression of STK4 is essential for the growth of HPV+ cervical cancer cells, it appears non-essential in driving YAP-dependent signalling in primary keratinocytes harbouring the HPV18 genome." (PMID 32555725, 2020). "Importantly, this pattern of STK4 expression was mirrored in cervical liquid based cytology samples from a cohort of HPV16+ patients representing cervical intraepithelial neoplasia (CIN) progression, which commonly precedes cervical cancer." (PMID 32555725, 2020). "STK4 protein levels were selectively decreased in HPV positive (HPV+) cervical cancer cells when compared with normal human keratinocytes (NHKs) or HPV negative (HPV-) cervical cancer cells." (PMID 32555725, 2020).
hepatocellular carcinoma (5 papers, 2023 to 2025). A malignant tumor that arises from hepatocytes. "Deficiency in STK4 leads to an increase in liver size and promotes hepatocellular carcinoma (HCC)." (PMID 37893233, 2023).
liver cancer (4 papers, 2020 to 2025). An epithelial or non-epithelial malignant neoplasm that arises from the liver. "The incidence of liver cancer is closely associated with the expression of STK4 in immune cells." (PMID 41011202, 2025). "Previous studies indicate that STK4 may be a diagnostic marker for colon cancer and liver cancer and be involved in colon cancer lymph node metastasis." (PMID 32741119, 2020). "We employed siRNA to effectively silence the expression of STK4 in HepG2 liver cancer cells to investigate the effect of STK4 gene knockdown on the anti-tumor effect of SS-b2 in vitro." (PMID 37893233, 2023). "Conditional STK4 ablation in mice suppresses liver cancer development through promoting YAP phosphorylation." (PMID 32741119, 2020). "Based on these previous findings, we aimed to investigate whether SS-b2 inhibits PLC development, particularly inflammation-related liver cancer, by targeting STK4/IRAK1 through in vivo and in vitro experiments." (PMID 37893233, 2023). "Recent studies have shown that SNORD88B is highly expressed in liver cancer stem cells (CSCs) and liver cancer samples, where it promotes the binding of XRCC5 to the STK4 promoter, thereby inhibiting STK4 transcription." (PMID 40584410, 2025). "The siRNA results showed that STK4 knockdown upregulated the expression of IRAK1 and thus the activation of NF-κB activity, consequently impairing SS-b2-induced inhibition of liver cancer development." (PMID 37893233, 2023). "Clinical studies have found substantial macrophage infiltration in the tumor tissues of patients with liver cancer, as well as a negative correlation between low STK4 levels and high IRAK1 levels within intracellular or peripheral blood mononuclear cells." (PMID 37893233, 2023). "Given the pivotal roles of STK4 and IRAK1 in the production of proinflammatory cytokines and cell proliferation in liver tumor cells, targeting STK4 and IRAK1 may present a novel strategy for inhibiting the development of inflammation-related liver cancer." (PMID 37893233, 2023). "Moreover, STK4 regulates the transcriptional activity of YAP/TAZ in the Hippo pathway, inhibits the proliferation of liver cancer cells, and degrades in macrophages by binding and phosphorylating IRAK1." (PMID 37893233, 2023). "The STK4 knockdown would upregulate IRAK1 and thus the activation of NF-κB activity revealed by the increase in the levels of proinflammatory cytokines, consequently impairing SS-b2-induced inhibition of liver cancer development." (PMID 37893233, 2023).
lung cancer (4 papers, 2019 to 2023). A malignant neoplasm involving the lung. "Daidzein action was mediated by restoring the STK4-induced YAP1 phosphorylation, and the components of Hippo pathway STK4 with significant inhibition of lung cancer cells." (PMID 31480720, 2019). "STK4 is investigated in many cancers, including hepatic cell carcinoma (HCC), malignant gliomas, lung cancer, head and neck squamous cell carcinoma, prostate cancer, and colon cancer." (PMID 32741119, 2020). "Quantitation of STK4 expression in nontumor and tumor tissues showed that STK4 was preferentially expressed in nontumor tissues of colon, liver, and stomach when compared to breast and lung cancer." (PMID 32741119, 2020).
neutropenia (4 papers, 2012 to 2024). A decrease in the number of neutrophils found in the blood. "This suggests some eventual interplay between CXCR4-dependant signalling and GATA2 that could account for the manifestations of neutropenia and warts of the GATA2 syndrome and beyond, of the more recently described Serine threonine kinase 4 (STK4)-linked syndrome." (PMID 23009155, 2012).
pancreatic cancer (4 papers, 2022 to 2025). "Promoter hypermethylation of STK4 was also reported in in human sarcomas and pancreatic cancer." (PMID 38627856, 2024). "However, miR-1178-3p promoted nasopharyngeal cancer and pancreatic cancer advancement by targeting STK4, p21, and CHIP, respectively, which might be related to the specificity of tumor tissue or cells." (PMID 35902926, 2022).
B cell lymphomas (3 papers, 2020 to 2022). "STK4-deficiency is associated with plasma cell hyperplasia and EBV+ B-cell polymorphous LP, and B-cell lymphomas showing plasmacytic differentiation." (PMID 35603189, 2022). "Serine/threonine-protein kinase 4 (STK4) deficiency, has been associated with nodal and extra-nodal EBV+ LP and B-cell lymphoma suggesting the role of EBV infection in inducing LP." (PMID 35603189, 2022). "In contrast, most malignancies reported in patients with STK4 deficiency are associated with prolonged EBV viremia, ultimately leading to the development of B cell lymphomas." (PMID 34427831, 2021).
nasopharyngeal carcinoma (3 papers, 2022 to 2024). A carcinoma arising from the nasopharyngeal epithelium. "MiR-1178-3p exerts an oncogenic role to facilitate nasopharyngeal carcinoma cell proliferation and motility by binding to STK4." (PMID 35813866, 2022).
Netherton syndrome (3 papers, 2015 to 2023). Netherton syndrome (NS) is a skin disorder characterized by congenital ichthyosiform erythroderma (CIE), a distinctive hair shaft defect (trichorrhexis invaginata; TI) and atopic manifestations. "Cutaneous viral infections are described in CARD11, LCK, NEMO, GATA2, STK4, DOCK8, and STAT2 deficiencies, STAT1 GOF, Netherton syndrome, WHIM syndrome, and WILD (warts, depressed cell‐mediated immunity, primary lymphedema, and anogenital dysplasia) syndrome." (PMID 37102642, 2023).
primary immunodeficiency (3 papers, 2014 to 2018). "Here we report on two patients with primary immunodeficiency due to homozygous STK4 mutations that were both initially clinically diagnosed as potentially ALPS like." (PMID 30386345, 2018). "We report a novel primary immunodeficiency, and a differential molecular diagnosis to CXCR4‐,DOCK8‐,GATA2‐,MAGT1‐,MCM4‐,STK4‐,RHOH‐,TMC6‐, and TMC8‐related diseases." (PMID 27896283, 2016).
viral infections (3 papers, 2017 to 2021). "Human STK4 deficiency is a primary immunodeficiency syndrome associated with recurrent bacterial and viral infections, mucocutaneous candidiasis, cutaneous warts, and skin abscesses." (PMID 32118703, 2020). "Overall, the suboptimal IFN signaling may contribute to the T cell immunodeficiency and the vulnerability of STK4-deficient patients to viral infection and cancer development." (PMID 34427831, 2021).
atopic dermatitis (2 papers, 2022 to 2024). "Allergic manifestations are also reported in STK4 deficiency (asthma, atopic dermatitis)." (PMID 39339890, 2024).
colon cancer (2 papers, 2020 to 2023). "Here, we found that STK4 was significantly downregulated in colon cancer and was associated with distal metastasis and poor survival." (PMID 32741119, 2020). "STK4 has been studied in many cancers with previous studies indicating an involvement in colon cancer lymph node metastasis and highlighting its potential as a diagnostic marker for colon cancer." (PMID 32741119, 2020). "Our study shows that STK4 is frequently defecting in colon cancer and the loss of STK4 may be important in the acquisition of metastatic phenotype of colon cancer." (PMID 32741119, 2020). "This may suggest that STK4 knockdown causes β‐catenin phosphorylation failure and subsequently β‐catenin accumulation, consequently leading to anchorage‐independent growth and metastasis in colon cancer." (PMID 32741119, 2020). "Our data also show that the change in STK4 levels negatively regulates β‐catenin‐mediated cell growth and cancer metastatic ability of colon cancer." (PMID 32741119, 2020). "Intrasplenic injection of cells expressing Scr and STK4‐shRNAs was the other in vivo metastasis model used to investigate the liver metastatic ability of colon cancer cells." (PMID 32741119, 2020). "Taken together, our findings showed that STK4 was downregulated in colon tumors and correlated with the poor survival of colon cancer patients." (PMID 32741119, 2020). "Subsequently, the expression dynamics of STK4 were further examined by using colon cancer TMA with complete follow‐up data." (PMID 32741119, 2020). "The relationship between STK4 expression and clinicopathological factors in 140 colon cancer patients." (PMID 32741119, 2020). "The quantification of luciferin signal indicated that STK4 knockdown significantly increased colon cancer metastasis rate (chi‐square test, P = 0.008)." (PMID 32741119, 2020). "The quantification of luciferin signals indicated that STK4 knockdown significantly increased colon cancer liver metastasis rate (chi‐square test, P = 0.025)." (PMID 32741119, 2020). "Nude mice subcutaneously injected with colon cancer cells expressing Scr and STK4‐shRNAs were used to evaluate tumor initiation ability." (PMID 32741119, 2020). "Taken together, our data indicated that low STK4 was correlated with poor outcomes in colon cancer patients." (PMID 32741119, 2020). "Our data show that shRNA‐mediated STK4 knockdown in colon cancer cells increases the abilities of cell migration and invasion, tumor formation, and capacities of sphere forming." (PMID 32741119, 2020). "The relationship between STK4 expression and clinicopathological factors was further analyzed in 140 colon cancer patients." (PMID 32741119, 2020). "In conclusion, STK4 plays an important role through interaction with β‐catenin in colon cancer disease models." (PMID 32741119, 2020). "Two ways of demonstrations by overexpression and knockdown of STK4 in colon cancer cells can conclude that STK4 levels were inversely correlated with CD133 expression." (PMID 32741119, 2020). "Downregulation of STK4 promotes colon cancer invasion/migration." (PMID 37019990, 2023). "STK4 downregulation enhances tumor growth of colon cancer through blocking β‐catenin degradation." (PMID 32741119, 2020). "Our results support that STK4 may act as a potential candidate for the assessment of β‐catenin‐mediated colon cancer prognosis." (PMID 32741119, 2020). "Our study has provided insights into the role of STK4 in β‐catenin‐mediated colon cancer." (PMID 32741119, 2020). "Taken together, these results indicated that STK4 interacted with β‐catenin in colon cancer cells." (PMID 32741119, 2020). "Thus, STK4 may be a new candidate for tumor suppressor gene replacement‐mediated colon cancer therapy." (PMID 32741119, 2020). "Thus, it implies that STK4 may suppress anchorage‐independent growth of colon cancer via downregulation of β‐catenin." (PMID 32741119, 2020). "This suggests that STK4 downregulation may facilitate colon cancer metastasis." (PMID 32741119, 2020).
colon cancer (continued). "However, the role of STK4 in colon cancer cell metastasis has remained unclear." (PMID 32741119, 2020). "However, the role of STK4 defect in promotion of the progression of colon cancer is still unclear." (PMID 32741119, 2020). "However, the role of STK4 defect in promoting colon cancer progression is still understudied." (PMID 32741119, 2020). "Thus, our data may suggest that STK4 is involved in the regulation of anchorage‐independent growth of colon cancer and its downregulation may consequently promote colon cancer metastasis." (PMID 32741119, 2020).
combined immunodeficiency (2 papers, 2016 to 2021). A broad classification of inherited disorders presenting at birth that affect both the cell-mediated and humoral aspects of the immune response. "Our current genetic findings suggest a higher mortality rate on special molecular defects associated with deficiency of the IL-1 receptor (DIRA deficiency), STK4 deficiency (combined immunodeficiency), and RAB27A deficiency (diseases of immune dysregulation) with COVID-19." (PMID 33263173, 2021). "Recently, two studies have identified MST1 deficiency as the cause of combined immunodeficiency (CID) in three different families with homozygous nonsense mutations in the STK4 gene." (PMID 26801501, 2016).
eosinophilia (2 papers, 2020 to 2022). "We observed elevated levels of IgE in 12 children—8 had OS, 1 had eczema and STK4 defect, and 3 had unexplained eosinophilia." (PMID 33628209, 2020).
Hepatic fibrosis (2 papers, 2018 to 2025). The presence of excessive fibrous connective tissue in the liver. "Studies have shown that STK4 and TRIB3 further participate in the occurrence and development of liver fibrosis by regulating the level of autophagy." (PMID 40368138, 2025). "•Three dysregulated kinases, STK4, GSK3α, and CDK11B, were screened out in mouse liver fibrosis." (PMID 40368138, 2025). "Our study further validated the aberrant activation of STK4 (serine/threonine-protein kinase 4), GSK3α (glycogen synthase kinase 3α), and CDK11B (cyclin-dependent kinase 11B) in liver fibrosis mice and found that their small-molecule inhibitors have antihepatic fibrosis effects." (PMID 40368138, 2025).